SEMA4B (semaphorin 4B)
Diseases named in the same sentence as SEMA4B in open-access papers (continued):
Sharing a sentence is not in itself a finding about the gene and the disease.
tumor (14 papers, 2018 to 2025). "Both circSEMA4B and the novel encoded protein SEMA4B-211aa were expressed at low levels in BC, and exerted as tumor suppressors in vivo and in vitro." (PMID 36115854, 2022). "CircSEMA4B exerted its tumor suppressive effects by encoding a novel protein SEMA4B-211aa, which could hinder the phosphorylation of AKT through regulating the formation of second messenger PIP3." (PMID 37626035, 2023). "As circSEMA4B could encode SEMA4B-211aa, it is necessary to further study whether circSEMA4B itself or the encoded protein SEMA4B-211aa exert the tumor suppressor role in BC." (PMID 36115854, 2022). "Sema4B has been implicated in both tumor invasion and proliferation, mostly in lung cancer cells." (PMID 29311693, 2018). "The functional investigation showed that both circSEMA4B and SEMA4B-211aa exert as tumor suppressors in BC." (PMID 36115854, 2022). "SEMA4B expression was significantly positively correlated with tumor infiltration of MDSCs (R = 0.368, p<0.001) and Tregs (R = 0.143, p<0.05)." (PMID 35676688, 2022). "We examined SEMA4B-211aa expression in BC, and found that SEMA4B-211aa was lowly expressed in BC tissues and cell lines, indicating it a tumor suppressor in BC." (PMID 36115854, 2022). "And the effect of SEMA4B on tumor growth and immune infiltration was explored in C57BL/6 mice tumor-bearing models." (PMID 35676688, 2022). "In future studies, we will focus on the correlation between SEMA4B and the recruitment of CTL, B cells, polarization of TAMs and tumor-associated fibroblasts." (PMID 35676688, 2022). "In this model we found that tumors are formed in both cell lines, although the size of the tumor volume and weight was markedly reduced in Sema4B knockdown cells." (PMID 29311693, 2018). "To test the impact on tumor formation, we used a xenograft model to begin validating the proliferative and survival effects of Sema4B in vivo." (PMID 29311693, 2018). "Among the known salivary extracellular RNA biomarkers examined in this study, the pre-operative expression levels of PPL, SEMA4B, and miR140-5p were significantly correlated with high tumor burden (which we defined as stages III and IV), along with age and sex." (PMID 40429589, 2025). "Recent reports also support the critical role of SEMA4B in NSCLC tumor progression." (PMID 40155749, 2025). "We supposed that SEMA4B might mediate tumor immune evasion by stimulating recruitment and infiltration of immunosuppressive cells, and the latter in the TME of LUAD contributed to poor prognosis." (PMID 35676688, 2022). "Importantly, as shown in the allograft model of Lewis lung cancer, SEMA4B knockdown decreased the enrichment of tumor infiltrating T-regs and MDSCs." (PMID 35676688, 2022). "However, the functional investigation showed that both circSEMA4B and SEMA4B-211aa exert as tumor suppressors in BC progression in vivo and in vitro." (PMID 36115854, 2022). "Importantly, in vivo study verified that the infiltration of T-regs and MDSCs in tumor microenvironment (TME) of Xenograft tissues was decreased after SEMA4B silencing." (PMID 35676688, 2022). "We also proved SEMA4B could promote tumor proliferation in Lewis lung cancer (LLC) both in vitro and in vivo." (PMID 35676688, 2022). "However, some possible reasons might include SEMA4B exhibited a dual role by demonstrating anti-tumor and pro-tumor effects." (PMID 35676688, 2022). "To investigate the fate of SEMA4B in vivo, we injected 2 × 106 shSEMA4B/shCtrl-expressing bioluminescent LLC tumor cells subcutaneously to thigh of C57BL/6 mice to monitor tumor growth." (PMID 35676688, 2022). "Experimental evidence in vivo, in mouse models, indicated that Sema4B expression in NSCLC is a critical determinant of tumor progression, and suggested its relevance as novel therapeutic target in this tumor type 82." (PMID 33537086, 2021). "By contrast, SEMA4B, KRT1, KRT9, FBLN1, and PTGDS are involved in the anti-invasive activity of tumor cells." (PMID 32953262, 2020).
tumor (continued). "Our results showed that SEMA4B was highly expressed in LUAD tissues and positively correlated with tumor pathological stage, T and N stage, but not with gender, age and smoking status." (PMID 35676688, 2022).
cancer (9 papers, 2015 to 2025). A tumor composed of atypical neoplastic, often pleomorphic cells that invade other tissues. "Thus, we conclude that although the shRNA effects on proliferation are the result of an off target effect of shRNA, the reduced clonality of the cells, confirmed by CRISPR, probably indicates that certain Sema4B splice variants do have a role in some aspects of cancer properties, at least in U87-MG." (PMID 29311693, 2018). "Immunohistochemical analysis showed that 6 gene (NLRX1, AKT1, CSRP1, LEP, MUC4 and SEMA4B) of 10 genes were abnormal expressions between cancer and paracancer tissue." (PMID 36817485, 2023). "Recently, a propensity to develop malignant tumors have also been observed in patients with high level of SEMA4B expression." (PMID 35676688, 2022). "To provide a comprehensive evaluation of SEMA4B expression in malignances, we compared the expression of SEMA4B across 33 TCGA cancer types." (PMID 35676688, 2022). "An earlier study showed that Sema4B is phosphorylated at serine 825 in some cancer cell lines stimulated with growth factors such as EGF." (PMID 26464987, 2015). "Recent work identified Ser825 as a site of Sema4B phosphorylation following mitogen stimulation in cancer cells." (PMID 26464987, 2015). "In the pan-cancer analysis, SEMA4B showed the highest expression levels among all the SEMAs." (PMID 40103807, 2025). "In addition, we observed the expression dysregulations of NLRX1, AKT1, CSRP1, LEP, MUC4 and SEMA4B in cancer tissues by immunohistochemistry." (PMID 36817485, 2023). "We found that SEMA4B was significantly upregulated in most types of cancers, including LUAD." (PMID 35676688, 2022). "Moreover, SEMA4B and HOOK2 were significantly associated with MSI in more than 10 cancers." (PMID 40574864, 2025). "It is possible that SEMA4B could play a dual role in the development of certain cancers." (PMID 34485161, 2021).
infection (2 papers, 2018 to 2023). The state of being infected such as from the introduction of a foreign agent such as serum, vaccine, antigenic substance or organism. "Using qPCR, we monitored the level of Sema4B expression in U87-MG cells at different time points after infection." (PMID 29311693, 2018). "These two infection cycles were designed to increase probability of a complete deletion event of the Sema4B locus." (PMID 29311693, 2018). "By 48 h there was a significant reduction in expression, and by 72 h after infection there was a consistent reduction of about 70–90% in Sema4B expression, depending on the sequence used." (PMID 29311693, 2018). "At 24 h after infection, there was no change in Sema4B expression." (PMID 29311693, 2018).
SEMA4B also shares sentences with these, for which no sentence is quoted: cervical cancer (3 papers); disorders of psychological development (2); Intellectual disability (2); lymph node metastasis (2); brain injury (1); colorectal cancer (1); endometrial cancer (1); epidermolysis bullosa (1); esophageal squamous cell carcinoma (1); glioblastoma (1); liver cancer (1); neurodegenerative disease (1); ovarian carcinoma (1); pancreatic cancer (1); renal carcinoma (1); stomach cancer (1); systemic sclerosis (1); thymoma (1); thyroid cancer (1); triple-negative breast carcinoma (1); urothelial carcinoma (1).